CELA1 (chymotrypsin like elastase 1)
Description:
Serine proteases that hydrolyze many proteins in addition to elastin.
Synonyms: ELA1
Tractability: Small molecule: it belongs to a druggable protein family. Antibody: UniProt places it where antibodies can reach, with medium confidence; UniProt predicts a signal peptide or a membrane-spanning region; its Gene Ontology location is reachable by antibodies, with medium confidence. PROTAC: a small molecule that binds it is known.
Target class: Serine protease; Enzyme; Serine protease PA clan; Serine protease S1A subfamily; Protease
Gene: Protein-coding gene on chromosome 12 (51,328,442 to 51,346,679, reverse strand). Ensembl gene ENSG00000139610.
Subcellular location: Secreted
Gene Ontology:
Molecular function: serine-type endopeptidase activity
Biological process: inflammatory response; proteolysis
Cellular component: extracellular region
Genetic constraint (gnomAD): Loss-of-function variants: 27 observed, 29.38 expected, observed/expected ratio (o/e) 0.92, 90% interval 0.68 to 1.27. The upper end of that interval is the gene's LOEUF score, 1.27, which puts it in group 5 of 6, group 1 being the genes least tolerant of losing a copy. Missense variants: 252 observed, 281.53 expected, observed/expected ratio (o/e) 0.9, 90% interval 0.81 to 0.99. Synonymous variants: 121 observed, 117.04 expected, observed/expected ratio (o/e) 1.03, 90% interval 0.89 to 1.2.
Homologues: Orthologues: chimpanzee CELA1 (97% identical), macaque CELA1 (91% identical), rat Cela1 (88% identical), pig CELA1 (88% identical), rabbit CELA1 (85% identical), mouse Cela1 (84% identical), guinea pig CELA1 (81% identical), dog CELA1 (73% identical), tropical clawed frog cela1.2 (66% identical), zebrafish cela1.6 (61% identical), zebrafish cela1.3 (59% identical), zebrafish cela1.4 (57% identical), and 5 more. Paralogues in human: CELA2A (55% identical), CELA2B (54% identical), CELA3A (53% identical), CELA3B (52% identical), ELANE (34% identical), PRTN3 (31% identical).
Diseases named in the same sentence as CELA1 in open-access papers:
CELA1 is named in the same sentence as 22 diseases in open-access papers, as found by Europe PMC text mining. Sharing a sentence is not in itself a finding about the gene and the disease. The quoted sentences say what the papers report.
emphysema (6 papers, 2019 to 2024). "We assert that the biology of CELA1 is distinct from that of other serine proteases and MMPs previously implicated in emphysema based on 3 findings." (PMID 38193533, 2024). "Taken together, these data show that Cela1-deficient mice have attenuation of at least 2 processes implicated in emphysema progression." (PMID 38193533, 2024). "In antisense oligonucleotide and genetic models of AAT-deficiency, Cela1−/− AAT-deficient mice are protected from emphysema." (PMID 38766202, 2024). "Analysis of his 100K genome using Exomiser identified a complex variant in a splice region of the CELA1 gene encoding an elastase involved in the pathogenesis of emphysema in α1-antitrypsin deficiency." (PMID 38790666, 2024). "We tested the role of CELA1 in emphysema development in this genetic model of AAT -deficiency following tracheal lipopolysacharide (LPS), 8 months of cigarette smoke (CS) exposure, aging, and a low-dose tracheal porcine pancreatic elastase (LD-PPE) model." (PMID 36865303, 2023). "Prior to developing anti-CELA1 therapies for AAT-deficient emphysema, an understanding of why and how CS exacerbates emphysema in Cela1 deficiency is needed." (PMID 36865303, 2023). "Cela1-deficient mice have preserved alveolar architecture in multiple models of emphysema." (PMID 38193533, 2024). "Cela1-deficiency is protective in a murine models of AAT-deficient emphysema." (PMID 38766202, 2024). "This study tested whether CELA1 is important in strain-mediated lung matrix destruction in non–AAT-deficient emphysema and the efficacy of CELA1 neutralization." (PMID 38193533, 2024). "Based upon the premise that AAT neutralization of CELA1 plays a key role in the pathogenesis of emphysema in AAT-deficiency, we sought to test whether Cela1-neutralization using KF4 antibody could protect AAT-deficient mice from emphysema and compare its efficacy with AAT replacement therapy." (PMID 38766202, 2024). "Second, CELA1 is expressed in AT2 cells, while most emphysema-associated proteases are expressed in myeloid cells." (PMID 38193533, 2024). "In this study, we showed that the KF4 anti-CELA1 antibody and purified human AAT were similarly effective at preventing emphysema in a mouse model of AAT-deficient emphysema and that KF4 has the potential for renal and hepatic toxicity." (PMID 38766202, 2024). "Following 8 months of CS exposure, Cela1–/– mice had less emphysema than WT mice, and they also had less age-related alveolar simplification." (PMID 38193533, 2024). "Although there were differences between models, there was a pattern of increased Cela1 expression in each mouse model of emphysema." (PMID 38193533, 2024). "CELA1 mRNA levels varied logarithmically but were higher in COPD with emphysema specimens compared with control." (PMID 38193533, 2024). "Third, Cela1–/– mice were protected from emphysema differently than what was observed in other protease-focused emphysema studies." (PMID 38193533, 2024). "CELA1 mediates emphysema progression in multiple models and is responsible for strain-induced lung elastase activity." (PMID 38193533, 2024). "As CELA1 is required for age-related alveolar simplification and elastin loss, it also links these 2 models to the accelerated aging model of COPD-associated emphysema." (PMID 38193533, 2024). "In all 3 models, Cela1–/– mice had less emphysema and preserved lung elastin despite increased lung immune cells." (PMID 38193533, 2024). "In conclusion, we found that the KF4 anti-CELA1 antibody and purified human AAT were similarly effective at preventing emphysema in a mouse model of AAT-deficient emphysema but that there was no benefit to combined therapy." (PMID 38766202, 2024). "In the LD-PPE model, AAT -/- mice developed progressive emphysema from which Cela1 -/- &AAT -/- mice were protected." (PMID 36865303, 2023).
emphysema (continued). "As one of the digestive enzymes that can be covalently neutralized by AAT and important in emphysema development, we first examined the expression of chymotrypsin-like elastase 1 (Cela1)." (PMID 33539438, 2021). "CELA1 may provide a mechanistic link between the protease-antiprotease and the structure-function models of emphysema." (PMID 38193533, 2024). "Mouse models of lung injury and emphysema have increased Cela1 expression." (PMID 38193533, 2024). "CELA1 mechanistically links the protease-antiprotease and the biomechanical models of emphysema." (PMID 38193533, 2024). "Since most proteases reported to have a role in emphysema are expressed by leukocytes and CELA1 is expressed in AT2 cells, we wondered whether there might be distinct remodeling programs that could be identified in human lung." (PMID 38193533, 2024). "KF4 anti-CELA1 antibody prevented emphysema in PPE and cigarette smoke models in wild type mice." (PMID 38766202, 2024). "Chymotrypsin-like elastase 1 ( CELA1 ) is a serine protease that is neutralized by α1-antitrypsin (AAT) and prevents emphysema in a murine antisense oligonucleotide model of AAT-deficient emphysema." (PMID 36865303, 2023). "Chymotrypsin-like Elastase 1 (CELA1) is a serine protease neutralized by AAT and is important in emphysema progression." (PMID 38766202, 2024). "CELA1 is neutralized by AAT and is required for development of emphysema in an antisense oligonucleotide mouse model of AAT-deficient emphysema." (PMID 38193533, 2024). "Chymotrypsin-like elastase 1 (CELA1) is a serine protease that binds and cleaves lung elastin in a stretch-dependent manner and is required for emphysema in a murine antisense oligonucleotide model of α-1 antitrypsin (AAT) deficiency." (PMID 38193533, 2024). "Since Cela1–/– mice demonstrated late protection against emphysema in the PPE model, we compared emphysema in IgG- and KF4-treated mice beginning at the time of injury and 7 days after injury." (PMID 38193533, 2024). "CELA1-mediated lung matrix remodeling in response to strain is an important contributor to postnatal airspace simplification, and we believe that KF4 could be developed as a lung matrix–stabilizing therapy in emphysema." (PMID 38193533, 2024). "Cela1–/– mice were not protected from initial injury and airspace destruction 21 days after administration of tracheal PPE, but unlike WT mice, they did not demonstrate emphysema progression at 42 and 84 days." (PMID 38193533, 2024).
breast carcinoma (2 papers, 2012 to 2022).
autoimmune disease (1 paper, 2024). A disorder resulting from loss of function or tissue destruction of an organ or multiple organs, arising from humoral or cellular immune responses of the individual to their own tissue constituents. "This might be suggesting that the CELA1-encoded elastase could act as a protease in antigen-presenting cells and when malfunctioning contributes to autoimmune disease." (PMID 38790666, 2024).
chronic pancreatitis (1 paper, 2016). A chronic inflammatory process causing damage and fibrosis of the pancreatic parenchyma. "CELA1 has also been linked to chronic pancreatitis, as patients with chronic pancreatitis commonly have very low levels of elastase." (PMID 27142762, 2016).
Sjögren’s syndrome (1 paper, 2024). "CELA1 variants have been found in individuals with multiple autoimmune syndrome and Sjögren’s syndrome." (PMID 38790666, 2024).
Tetralogy of Fallot (1 paper, 2017). A congenital cardiac malformation comprising pulmonary stenosis, overriding aorta, ventricular septum defect, and right ventricular hypertrophy. "Analysis using Gene Ontology /pathway, Online Mendelian Inheritance in Man, PubMed and other databases revealed that PEX5, NACA, ATXN2, CELA1, PCDHB4 and CTBP1 were associated with Tetralogy of Fallot." (PMID 29291004, 2017). "Our findings identify PEX5, NACA, ATXN2, CELA1, PCDHB4 and CTBP1 mutations as underlying genetic causes of isolated tetralogy of Fallot." (PMID 29291004, 2017).
tumor (7 papers, 2010 to 2024). "This evaluation detected CELA1 and CTRL primarily in tumor cells, although expression was detected in normal epithelial cells." (PMID 27081040, 2016). "Moreover, in tumor tissues, CELA1 and CTRL were detected in both tumor and stromal cells, and the levels of the two proteases were significantly increased in the tumor cells not in stromal cells." (PMID 27081040, 2016). "Therefore, all MRM results demonstrated that the serum abundance of the six proteins, CELA1, CEL2A, chymopasin, CTRB1, TRY2, and TRY4, reflected tumor development and served as CRC serum biomarkers in this mouse model." (PMID 27081040, 2016). "Thus, changes in Gast, Ccla3, Glycam1, Spp1, Serpina1a, Cela1, Cldn2, and Fabp2 are a result of GW501516 treatment and are not tumor specific." (PMID 21318167, 2010).
CELA1 also shares sentences with these, for which no sentence is quoted: pancreatic cancer (7 papers); cancer (3); pancreatitis (2); Autoimmunity (1); coronary artery disease (1); dyslipidaemia (1); dyslipidemia (1); Endemic Nephropathy (1); hepatocellular carcinoma (1); ischemic stroke (1); liver disease (1); lung diseases (1); Obesity (1); pancreatic acinar cell carcinoma (1); pancreatic autoimmunity (1).